RNU6-1106P (RNA, U6 small nuclear 1106, pseudogene)
Gene: Small nuclear RNA gene on chromosome 6 (105,045,562 to 105,045,668, reverse strand). Ensembl gene ENSG00000212147.
Homologues: Orthologues: chimpanzee U6 (100% identical), macaque U6 (83% identical), dog U6 (69% identical), mouse Gm22960 (68% identical), guinea pig U6 (66% identical), mouse Gm25819 (63% identical), rat LOC120095718 (56% identical), guinea pig U6 (53% identical). Paralogues in human: RNU6-38P (79% identical), RNU6-1145P (78% identical), RNU6-1316P (78% identical), RNU6-411P (78% identical), RNU6-468P (78% identical), RNU6-639P (78% identical), RNU6-1005P (77% identical), RNU6-20P (77% identical), RNU6-574P (77% identical), RNU6-616P (77% identical), RNU6-658P (77% identical), RNU6-73P (77% identical), and 1286 more.